ZNF433 (zinc finger protein 433)
Description:
May be involved in transcriptional regulation.
Synonyms: FLJ40981
Tractability: PROTAC: ubiquitination databases record sites on it.
Gene: Protein-coding gene on chromosome 19 (12,014,715 to 12,035,741, reverse strand). Ensembl gene ENSG00000197647.
Subcellular location: Nucleus
Subcellular location (Human Protein Atlas): Nuclear bodies
Pathways (Reactome):
Gene expression (Transcription): Generic Transcription Pathway
Gene Ontology:
Molecular function: protein binding; DNA-binding transcription factor activity, RNA polymerase II-specific; RNA polymerase II transcription regulatory region sequence-specific DNA binding; sequence-specific double-stranded DNA binding
Biological process: regulation of transcription by RNA polymerase II; regulation of DNA-templated transcription
Cellular component: nucleus
Genetic constraint (gnomAD): Loss-of-function variants: 8 observed, 8.28 expected, observed/expected ratio (o/e) 0.97, 90% interval 0.56 to 1.68. That is too few expected variants to judge how well the gene tolerates losing a copy. Missense variants: 734 observed, 828.73 expected, observed/expected ratio (o/e) 0.89, 90% interval 0.83 to 0.94. Synonymous variants: 272 observed, 282.4 expected, observed/expected ratio (o/e) 0.96, 90% interval 0.87 to 1.07.
Homologues: Orthologues: chimpanzee ZNF433 (99% identical), macaque ZNF433 (95% identical), rat Zfp617 (30% identical), mouse Zfp961 (30% identical). Paralogues in human: ZNF700 (59% identical), ZNF709 (57% identical), ZNF44 (51% identical), ZNF443 (51% identical), ZNF791 (51% identical), ZNF823 (50% identical), ZNF799 (50% identical), ZNF14 (48% identical), ZNF441 (48% identical), ZNF442 (48% identical), ZNF878 (48% identical), ZNF844 (43% identical), and 3 more.
Diseases named in the same sentence as ZNF433 in open-access papers:
ZNF433 is named in the same sentence as 19 diseases in open-access papers, as found by Europe PMC text mining. Sharing a sentence is not in itself a finding about the gene and the disease. The quoted sentences say what the papers report.
renal carcinoma (3 papers, 2021 to 2025). A carcinoma arising from the epithelium of the renal parenchyma or the renal pelvis. "This trend implies that ZNF433 may function as a tumor suppressor and could serve as a stage-associated prognostic biomarker in renal cancers." (PMID 40636694, 2025). "The results showed lower levels of ZNF433 protein in renal cancer cells." (PMID 40636694, 2025). "Additionally, the expression of the ZNF433 gene was validated in three renal cancer cell lines (A-498, 786-O, and Caki-1) and one normal kidney cell line (HK-2)." (PMID 40636694, 2025). "Finally, ZNF433 expression was suppressed in both renal carcinoma subtypes (p < 0.001), with the more aggressive subtype ccB exhibiting the lowest level of mRNA expression." (PMID 34439859, 2021). "Renal cancer tissues had “low” or “not detected” staining with “weak” intensities, whereas all normal tissues were described as having “medium” staining with “moderate” intensities, thereby suggesting that the ZNF433 protein is downregulated in renal carcinomas." (PMID 34439859, 2021).
clear cell renal cell carcinoma (2 papers, 2021 to 2025). "Lower expression of ZNF433 mRNA was associated with a poorer prognosis in patients with clear-cell renal cell carcinomas (HR, 0.45; 95% CI, 0.33–0.6; p = 8.5 × 10−8)." (PMID 34439859, 2021). "Given the scarcity of information regarding the transcriptional targets of ZNF433, comprehensive analysis is required to identify and validate ZNF433 gene targets, as well as transcription regulators of ZNF433, particularly in clear-cell renal cell carcinomas." (PMID 34439859, 2021). "To characterize ZNF433, we examined ZNF433 expression in different clinicopathological features of clear-cell renal cell carcinoma." (PMID 34439859, 2021). "ZNF433 was significantly downregulated (p < 0.05) in the head and neck, clear-cell renal cell carcinoma, renal papillary, renal chromophobe, lung, and thyroid cancers." (PMID 34439859, 2021). "Likewise, the hypermethylation of ZNF433 has been related to the progression of clear cell renal cell carcinoma and the differential methylation and overexpression of DAXX in the progression of leiomyosarcoma." (PMID 39858027, 2025). "We examined the expression of ZNF433 target genes in clear-cell renal cell carcinoma." (PMID 34439859, 2021). "ZNF433 gene and protein expression are reduced in clear-cell renal cell carcinoma." (PMID 34439859, 2021). "It was concluded from this study that gene expression of ZNF433 is associated with cancer progression and poorer prognosis, and that ZNF433 behaves in a manner that suggests that it is a prognostic marker and a possible tumor-suppressor gene in clear-cell renal cell carcinoma." (PMID 34439859, 2021). "Here, we report that the ZNF433, a KRAB zinc-finger transcription family member, is downregulated in clear-cell renal cell carcinoma, and its expression is reduced in a stage-specific manner." (PMID 34439859, 2021).
prostate carcinoma (2 papers, 2025). A carcinoma that arises from epithelial cells of the prostate gland. "Additionally, ZNF433 is significantly upregulated in prostate cancer, where it promotes cancer cell proliferation, migration, and tumorigenicity by activating the β-catenin/TCF signaling pathway, making it a potential therapeutic target for prostate cancer." (PMID 40636694, 2025).
alcohol addiction (1 paper, 2025). "In addition, KEGG pathway analysis indicated that ZNF433 is associated with pathways such as transcriptional dysregulation in cancer, human herpesvirus 1 infection, alcohol addiction, and systemic lupus erythematosus." (PMID 40636694, 2025).
alcoholism (1 paper, 2025). "Additionally, KEGG enrichment analysis indicated that ZNF433 is primarily associated with pathways such as herpes simplex virus 1 infection, transcriptional dysregulation in cancer, alcoholism, and systemic lupus erythematosus." (PMID 40636694, 2025).
cholangiocarcinoma (1 paper, 2021). A carcinoma that arises from the intrahepatic biliary tree (intrahepatic cholangiocarcinoma) or from the junction, or adjacent to the junction, of the right and left hepatic ducts (hilar cholangiocarcinoma). "Conversely, ZNF433 was significantly upregulated (p < 0.05) in bladder, cholangiocarcinoma, liver, and uterine cancers." (PMID 34439859, 2021).
kidney cancer (1 paper, 2021). Primary or metastatic malignant neoplasm involving the kidney. "In conclusion, ZNF433 is a member of the KRAB-ZFTF subfamily, which is differentially expressed in several cancers; however, poor prognosis is largely associated with low expression in kidney cancers." (PMID 34439859, 2021).
cancer (3 papers, 2021 to 2025). A tumor composed of atypical neoplastic, often pleomorphic cells that invade other tissues. "In conclusion, this study provides the first multidimensional characterization of ZNF433 across various cancers, delineating its potential in diagnostic, prognostic, and personalized treatment applications." (PMID 40636694, 2025). "We have evaluated the potential of ZNF433 as a diagnostic and prognostic biomarker in cancer and further explored its underlying biological functions and associated signaling pathways through bioinformatics analyses." (PMID 40636694, 2025). "Genetic alteration analysis via cBioPortal identified ZNF433 mutations and amplifications across multiple cancers." (PMID 40636694, 2025). "Using the TCGA and TCGA+GTEx datasets, we evaluated the diagnostic value of ZNF433 across various cancers." (PMID 40636694, 2025). "This study presents the first comprehensive pan-cancer analysis of ZNF433, revealing its promising potential as a diagnostic and prognostic biomarker." (PMID 40636694, 2025). "We conducted multi-dimensional analyses using publicly available databases, including TCGA and GTEx, to evaluate ZNF433’s expression patterns, genetic mutations, survival outcomes, immune microenvironment interactions, and diagnostic potential across different cancers." (PMID 40636694, 2025). "Furthermore, we explored the potential association between ZNF433 alterations and clinical survival rates across different cancer types." (PMID 40636694, 2025). "Diagnostic analysis showed that ZNF433 has strong diagnostic potential in LAML and TGCT, and moderate diagnostic value in other cancers." (PMID 40636694, 2025). "In terms of diagnostic value, ROC analysis demonstrated that ZNF433 exhibits strong diagnostic potential in LAML and TGCT (AUC > 0.9), with moderate diagnostic efficacy in other cancers." (PMID 40636694, 2025). "Despite the growing body of research on KRAB-ZFPs, the role of ZNF433, a relatively less studied member of this family, remains poorly understood in the context of cancer." (PMID 40636694, 2025). "We observed a significant correlation between ZNF433 expression and immune infiltration in 27 cancer types." (PMID 40636694, 2025). "Correlations with tumor-infiltrating lymphocytes across multiple cancers supported ZNF433’s role in microenvironmental regulation." (PMID 40636694, 2025). "Due to the limited availability of normal specimens in the TCGA tumor samples, we utilized SangerBox to integrate transcriptomic data from three datasets (HPA, GTEx, and FANTOM5) to analyze ZNF433 expression in 34 cancer types." (PMID 40636694, 2025). "To investigate the relationship between ZNF433 expression and immunity, we conducted a systematic analysis correlating ZNF433 with immune features in the tumor microenvironment, commonly used in cancer research datasets." (PMID 40636694, 2025). "Our findings revealed that ZNF433 is significantly downregulated in most cancer types, with stage-dependent expression patterns observed in KIRC and KIRP." (PMID 40636694, 2025). "Survival analysis revealed that ZNF433 has cancer-type-specific prognostic effects: high expression is associated with improved OS in HNSC and KIRC, but with poorer DFS in ESCA and PRAD." (PMID 40636694, 2025). "Our findings provide new insights into the potential of ZNF433 as a cancer biomarker and therapeutic target, laying the foundation for future mechanistic studies and clinical applications." (PMID 40636694, 2025). "We next evaluated the correlation between ZNF433 expression and 44 common RNA modification regulators across different cancer types." (PMID 40636694, 2025).
cancer (continued). "To further investigate the potential of ZNF433 as a prognostic biomarker in cancer, we used SangerBox to analyze survival data from pan-cancer datasets, including TCGA, TARGET, and GTEx." (PMID 40636694, 2025). "Across all TCGA cancer types, ZNF433 expression exhibited a strong positive correlation with these genes." (PMID 40636694, 2025). "Analysis results indicate that ZNF433 is significantly downregulated in the majority of cancer types." (PMID 40636694, 2025). "To further investigate the expression patterns of the ZNF433 gene in human cancers, we conducted expression analyses using the TIMER2.0 online database." (PMID 40636694, 2025). "Based on these findings, we hypothesize that alterations in ZNF433 may contribute to cancer progression." (PMID 40636694, 2025). "In addition, the relationship between ZNF433 expression levels and various cancer pathological stages was analyzed using GEPIA2." (PMID 40636694, 2025). "Specifically, ZNF433 may influence molecules or pathways in the immune system, thereby impacting the growth and spread of cancer cells." (PMID 40636694, 2025). "We aim to investigate the role of the ZNF433 gene in human cancer." (PMID 40636694, 2025). "Furthermore, IHC analysis of 17 cancer tissues and their paired normal counterparts revealed reduced ZNF433 protein levels in the cancer tissues." (PMID 40636694, 2025). "Lastly, we examined ZNF433 expression across multiple cancers to ascertain if ZNF433 may be a common tumor marker." (PMID 34439859, 2021). "However, in cancer types such as DLBC, PAAD, and PRAD, ZNF433 exhibited a significant positive correlation with most immunoregulatory genes and immune checkpoint genes, suggesting a regulatory role for ZNF433 in the development of these cancers." (PMID 40636694, 2025). "Overall, these findings suggest that ZNF433 may play a crucial role in different cancers." (PMID 40636694, 2025). "Although previous studies have provided preliminary insights into the function of ZNF433 in individual cancers, systematic research on ZNF433 in the pan-cancer context is still lacking." (PMID 40636694, 2025). "Therefore, we assessed the correlation between ZNF433 gene expression and TMB/MSI across pan-cancer." (PMID 40636694, 2025). "Through our analysis of the relationship between ZNF433 expression and both immunoregulatory and immune checkpoint genes, we observed a significant negative correlation between ZNF433 and most of these genes in various cancer types, including BLCA, GBM, KIPAN, KIRC, SARC, and THCA." (PMID 40636694, 2025). "However, in the corresponding tumor tissue, ZNF433 expression demonstrates negative or weak staining characteristics, which indicate that the expression of ZNF433 protein is downregulated in these types of cancers." (PMID 40636694, 2025). "Specifically, ZNF433 expression was positively correlated with immune infiltration in TCGA-DLBC (N = 46, R = 0.32, P = 0.03), while a significant negative correlation was found in 26 other cancer types, including TCGA-GBM (N = 152, R = -0.51, P = 2.0e-11)." (PMID 40636694, 2025).
tumor (2 papers, 2021 to 2025). "ZNF433 expression was also closely associated with genomic instability markers, including tumor mutational burden (TMB), microsatellite instability (MSI), and mismatch repair (MMR) deficiencies." (PMID 40636694, 2025). "In contrast, ZNF433 expression is significantly downregulated in clear cell renal carcinoma (ccRCC), and its low expression is closely associated with advanced tumor stages, higher grades, increased metastasis risk, and poorer survival prognosis." (PMID 40636694, 2025). "The DSS analysis indicated that high expression of ZNF433 was associated with poor prognosis in three tumor types: TCGA-GBMLGG (N = 598, p = 5.3e-9, HR = 2.52 [1.85, 3.43]), TCGA-LGG (N = 466, p = 0.02, HR = 1.77 [1.09, 2.87]), and TCGA-PCPG (N = 170, p = 0.01, HR = 26.85 [2.15, 335.88])." (PMID 40636694, 2025). "Additionally, using GEPIA2, we retrieved the top 100 genes associated with ZNF433 from both tumor and normal tissues in the TCGA database and identified the five most significantly correlated genes." (PMID 40636694, 2025). "Therefore, ZNF433 represents a predictive risk factor for tumor progression, and may prove to be a possible therapeutic target in the treatment of ccRCC." (PMID 34439859, 2021). "Through the UALCAN portal, we assessed the methylation levels of the ZNF433 promoter in tumor and normal tissues." (PMID 40636694, 2025). "The results revealed significant upregulation of ZNF433 expression in seven tumor types, including GBM, GBMLGG, LGG, UCEC, ALL, LAML, and CHOL." (PMID 40636694, 2025). "Using the UALCAN portal, we evaluated the methylation levels of the ZNF433 promoter in both tumor and normal tissues." (PMID 40636694, 2025). "Increased promoter methylation levels of ZNF433 were also detected in tumor tissues at various stages of BRCA, COAD, CESC, HNSC, KIRC, KIRP, and LUAD." (PMID 40636694, 2025). "In both KIRC and KIRP, the expression of ZNF433 progressively decreases with advancing pathological stage, suggesting its potential involvement in tumor progression." (PMID 40636694, 2025). "In this study, data indicated that ZNF433 behaved in a consistent manner, with it being a prognostic marker and/or a putative tumor-suppressor gene." (PMID 34439859, 2021). "The downregulation of ZNF433 may be regulated by DNA methylation and is linked to mutations in key genes such as BAP1, KDM5C, and ALOX5, suggesting its potential role as a tumor suppressor." (PMID 40636694, 2025). "Notably, OV patients harboring ZNF433 mutations exhibited significantly reduced OS and DSS, implicating ZNF433 genomic alterations in tumor progression." (PMID 40636694, 2025). "Additionally, increased promoter methylation levels of ZNF433 were observed in tumor tissues across various stages of BRCA, COAD, CESC, HNSC, KIRC, KIRP, and LUAD." (PMID 40636694, 2025). "Previous studies have shown that ZNF844, a paralog of ZNF433, is also significantly downregulated in KIRC and is associated with poorer survival, advanced pathological stage, and higher tumor grade, suggesting its potential role as a tumor suppressor." (PMID 40636694, 2025). "Furthermore, ZNF433 exhibited significant regulatory roles within the tumor immune microenvironment." (PMID 40636694, 2025). "The role of ZNF433 in tumor development was further verified through the GEPIA2.0 database." (PMID 40636694, 2025). "Based on our investigation of ZNF433 protein expression in the HPA database, we provide immunohistochemistry (IHC) results of ZNF433 in tumor and normal tissues." (PMID 40636694, 2025). "Conversely, ZNF433 expression showed a significant negative correlation with TMB in BRCA (P < 0.001), KIPAN (P < 0.001), KIRC (P < 0.001), THCA (P < 0.01), READ (P < 0.05), PAAD (P < 0.01), CHOL (P < 0.05), and DLBC (P < 0.001) across eight tumor types." (PMID 40636694, 2025).
ZNF433 also shares sentences with these, for which no sentence is quoted: bladder cancer (1 paper); cervical cancer (1); cutaneous melanoma (1); hepatocellular carcinoma (1); leiomyosarcoma (1); lung carcinoma (1); papillary renal cell carcinoma (1); systemic lupus erythematosus (1); thyroid cancer (1); uterine cancer (1).